EED (embryonic ectoderm development)
Diseases named in the same sentence as EED in open-access papers (continued):
Sharing a sentence is not in itself a finding about the gene and the disease.
tumor (50 papers, 2010 to 2025). "EED was also identified as a hit in a recent CRISPR knockout screen in tumour spheres derived from H3-mutated and wild-type childhood HGG." (PMID 37161535, 2023). "Remarkably, opposite correlations were observed for EZH2, SUZ12, and EED in some cancers, with higher expression being associated with a longer survival, suggesting a tumor suppressor role for PRC2 in those cases." (PMID 34202528, 2021). "EED inhibitors display potent in vitro and in vivo efficacy in different tumor types, also in models harboring an EZH2 mutation leading to resistance to inhibitors." (PMID 28486411, 2017). "To further corroborate that PRC2 inactivation in various cancer contexts was associated with a cold TME, we identified available archival tumor tissues with confirmed PRC2 inactivation through EED or SUZ12 loss-of-function mutations by MSK-IMPACT and loss of H3K27me3 immunostaining by IHC." (PMID 35852856, 2022). "Transition from the benign to malignant state also coincides with rise of genomic instability, which likely accelerates loss of function of key tumor suppressors (e.g. EED, SUZ12) and affects copy-number status of multiple oncogenes and other tumor suppressor genes." (PMID 32642732, 2020). "EED loss may be the key to maintain an EZH2 high/H3K27me3 low state in other tumour types, or even in normal cells such as the oesophageal epithelium, and will warrant more study in the future." (PMID 28387316, 2017). "EZH2 and EED were predominantly localized to the nucleus in tumor cells, consistent with their known roles in chromatin modification." (PMID 40766612, 2025). "Overexpression of SUZ12 and EED protein was also detected in KIRC tumor tissues, albeit to a lesser extent than in LIHC." (PMID 39516467, 2024). "Currently, it has been reported that the pro-tumor activity of PRC2 is mainly associated with its EZH2, EED, and SUZ12 subunits." (PMID 36076977, 2022). "HDACi synergizes with EED inhibitor (EEDi) in vitro and together inhibited tumor growth in xenograft mice." (PMID 34654445, 2021). "The analysis of cBioPortal clinical data indicates that amplification of EZH2, SUZ12, and EED genes was not limited to one particular malignancy but varied between different tumor types." (PMID 34202528, 2021). "A prior study tried to discover an EED inhibitor with anti-cancer efficacy, and suggested that specific and direct inhibition of EED can result in tumor repression." (PMID 33882457, 2021). "The high EZH2, SUZ12, and EED expression in tumor samples has been attributed to the decreased patient survival in several tumor types." (PMID 34202528, 2021). "Measurement of tumor volume in mice from the 5th day showed slowed tumor growth and tumor weighting after euthanasia on the 30th day of inoculation revealed significant reduced tumor weight after EED knockdown." (PMID 33882457, 2021). "The tumor suppressive effects be realized through selective repression of H3K27me3 by concentration-dependently blocking the EZH2/EED axis and diminishing EZH2 levels." (PMID 33882457, 2021). "The analysis of tumor subtypes revealed a distribution of alterations in the EZH2, EED, and SUZ12 genes (amplifications, deep deletions, mutations, fusions, and multiple alterations) in the 20 most common tumor subtypes (at least 50 samples per each subtype)." (PMID 34202528, 2021). "Two tumours, cases 20 and 40, had a somatic mutation in addition to LOH (biallelic alterations) in EED and SUZ12, respectively." (PMID 32666581, 2020). "In contrast, loss-of-function mutations in PRC genes, such as EZH2, EED, SUZ12, BCOR, and BCORL1, have been found in various hematological malignancies, suggesting their tumor suppressor functions." (PMID 33374737, 2020).
tumor (continued). "MAK683, the embryonic ectoderm development protein (EED) inhibitor, can induce reduced tumor cell proliferation in EZH2 mutated cells through binding to EED to block the interaction between EED and EZH2." (PMID 33317571, 2020). "In this study, we found miR-590-3P inhibits cell cycle, proliferation, invasion and migration via EED in vitro, and suppresses tumor growth in vivo." (PMID 29262610, 2017). "Paired-Wilcoxon signed rank test showed a significant increase of EZH2 in metastatic tumor cells compared to primary tumor cells (p = 0.007); EED demonstrated an increased trend in 6 out of 8 paired samples (p = 0.054)." (PMID 23251464, 2012). "We validated the expression of EZH2 and its binding partner EED in purified tumor cells from 8 paired primary tumor and lymph node samples with real-time PCR." (PMID 23251464, 2012). "Interestingly, USP22 appears to selectively control EZH2 but not any other PCR2 complex proteins including EZH1, SUZ12, and EED in tumor cells." (PMID 41252204, 2025). "However, the data obtained in the present study, in agreement with data from the public database DepMap, indicated that only a subset of the SWI/SNF LOF tumor cells were sensitive to PRC2/EED perturbation." (PMID 39500892, 2024). "We also observed copy number gains in EZH2 (chr7:148,504,464–148,581,441), PTEN (with LOH, chr10:89,622,870–89,731,687), and EED (chr11:85,955,806–85,989,785) in both the cell line and tumor Like NF1, the tumor suppressor CDKN2A is frequently mutated in NF1-associated MPNSTs." (PMID 33707600, 2021). "In addition, a network of EZH2 and its interacting proteins (UBC, CDK1, HDAC1, SUZ12, EED) was found to participate in miR-26a-mediated tumor progression." (PMID 34381816, 2021). "However, the EED inhibitor MAK683 which targets the PRC2 complex just entered clinical phase 1 for different tumor types including prostate cancer." (PMID 28486411, 2017). "Additionally, the HDAC inhibitors Entinostat and Romidepsin have been shown to synergize with Doxorubicin in vitro, and inhibit tumor growth when combined with an embryonic ectoderm development (EED, a protein which is part of the PRC2 complex) inhibitor in vivo." (PMID 39518006, 2024). "Disrupting the interaction between EZH2 and EED may be helpful to tumor inhibition." (PMID 38629070, 2024). "When specificially examining the tumor samples alone, we found that the cycling HepT population expressed high levels of EZH2, SUZ12, and EED, along with cell cycle regulators MKI67, AURKB, ASPM, TOP2A, and HELLS." (PMID 40766612, 2025). "EZH2 and EED act as downstream regulators of this pathway, with phosphorylated E2F binding to the EZH2 and EED promoters, disrupting the tumor cell cycle and driving malignant progression." (PMID 40042761, 2025). "Previously, EZH2, SUZ12, EED, MTF2 and JARID2 have all been suggested to not only act as oncogenes, but also to have tumor suppressor activities, depending on the type of cancer." (PMID 38562687, 2024). "The tumour specificity of the gene knockout was tested in neural foetal stem cells (NSC), and our results show that the genes UBE2N, CHD4, LSM11, EED, KANSL1 and KANSL3 are essential for CSC growth and suggest them as therapeutic candidates in paediatric HGG." (PMID 37161535, 2023). "In multiple MLL1-rearranged leukaemia cells, 57 depleted EZH2, EED and SUZ12 and demonstrated the significant anti-tumour effect in a variety of cancer lines and patient-derived models as well as in multiple tumour cell line xenografted and PDX models." (PMID 37667522, 2023). "We found that the amplification of EZH2 as well as EED and SUZ12 subunits was not limited to a specific tumor type." (PMID 34202528, 2021).
tumor (continued). "Here, we performed a comprehensive analysis of data in the genomic and transcriptomic (cBioPortal, KMplot) database portals of clinical tumor samples and evaluated clinical correlations of EZH2, SUZ12, and EED." (PMID 34202528, 2021). "In total, in 10 tumor types, the higher expression of at least one of the EZH2, SUZ12, or EED genes was significantly correlated with poor prognosis (logrank p < 0.05)." (PMID 34202528, 2021). "It appears that at least in NF1-associated MPNSTs, progression from benign to malignant status frequently proceeds through sequential inactivation of three tumor suppressors: NF1, CDKN2A/B, and SUZ12 and/or EED (PRC2 complex)." (PMID 32642732, 2020). "On the contrary, EZH2, EED and SUZ12 were substantially overexpressed in tumor samples (n = 22, p < 0.01)." (PMID 27472460, 2016). "We examined the significant genes from Ectoderm (FDR < 0.0003 in 5 tumor types) and Epidermis development (FDR < 7.7×10-5 in 5 tumor types) in each cancer type in the context of the occupancy of PRC2 components SUZ12 and EED, and H3K27me3." (PMID 23033966, 2012). "By microarray network analysis, we found an increased expression of polycomb repression complex 2 (PRC2) core subunits EED and EZH2 in lymph node metastatic tumor cells over primary tumor cells which were validated through real-time PCR." (PMID 23251464, 2012). "Additionally, we performed immunohistochemical staining of EZH2, EED, SUZ12, and H3K27me3 on archived UTUC tumor tissues to reveal the presence of PRC2." (PMID 36428492, 2022). "Interestingly, the mean H-Score for EZH1 was significantly higher in P-NEN compared to GEP-NEN but similar for all tumor grades, while SUZ12 and EED were barely expressed across all grades and entities." (PMID 35740494, 2022). "The PRC2 complex is composed of several subunits (EZH2, EED, SUZ12, JARID2 and Rbap46.48), which are often amplified in MB, and their actions leads to an elevated level of H3K27me3 by repressing specific tumor suppressor genes, thus facilitating tumor development." (PMID 36968588, 2023). "Moreover, EEDi-5285 is the most potent EED inhibitor that has been reported, and it achieves complete and long-lasting tumor regression in mice, further suggesting great potential for the treatment of PRC2-dependent cancers by inhibiting the EED-H3K27me3 interaction." (PMID 36076977, 2022). "Similar to that of Usp22-targeted deletion, treatment of tumor cells with USP22i-S02 led to a substantial reduction in EZH2, but not EED, EZH1, and SUZ12." (PMID 41252204, 2025). "In contrast, SUZ12 did not co-localize with EZH2 or EED, suggesting a possible disruption of PRC2 complex formation or altered subcellular dynamics in the tumor context." (PMID 40766612, 2025).
cancer (45 papers, 2012 to 2025). A tumor composed of atypical neoplastic, often pleomorphic cells that invade other tissues. "Key RNA-binding residues are spread out along the surface of EZH2, with other subunits including EED also contributing, and missense mutations of some of these residues have been found in cancer patients." (PMID 29185984, 2017). "EED encodes a polycomb protein that regulates epithelial-mesenchymal transition of cancer cells induced by TGF-β." (PMID 29262610, 2017). "EED, a core part of the PRC2, has in itself been associated with several forms of cancer, as has the PRC2 complex." (PMID 37161535, 2023). "Taken together, these results suggest that BMI1/RING1B degraders, such as MS147, but not the parent EED binder or EED/PRC2 degraders, can effectively suppress the proliferation of cancer cell lines that are insensitive to EZH2 knockout or EED/PRC2 degraders." (PMID 36737841, 2023). "This function of PRC2 represents a target for anticancer therapies e.g., through EED inhibition associated to de-repression of SASP-encoding genes and entry of proliferative cancer cells in a senescent state." (PMID 37842084, 2023). "According to previous studies, genetic alterations including loss of NF1, EED, and SUZ12, have been demonstrated to activate the RAS/MAPK pathway in various human cancers including MPNSTs." (PMID 35875109, 2022). "EED is a component of the polycomb repressor complex involved in the pathogenesis of numerous cancer types." (PMID 35777959, 2022). "Allosteric EED inhibitors, PRC2 disrupters, and EZH2/EED degraders can inhibit the growth of cancers insensitive to EZH2 enzymatic inhibitors, although the full utility of these compounds remains to be explored." (PMID 34617019, 2021). "For example, gain-of-function mutations in EZH2, EED or SUZ12 occur in multiple cancer types, and both EZH2 and EED are current targets for cancer therapy." (PMID 30005706, 2018). "Promoters that become hypermethylated by depletion of EED or WDR5 were more than twice as likely to be represented among genes hypermethylated in cancer." (PMID 25071008, 2014). "Moreover, it has been shown that the loss of and mutations in EED, EZH2, and SUZ12 promote defects during gastrulation in development, and are implicated in the development of different cancers." (PMID 36135315, 2022). "Finally, we generated a Python application to analyze the correlation of EZH2/SUZ12/EED gene knockouts by CRISPR with the alterations detected in the cancer cell lines using DepMap data." (PMID 34202528, 2021). "Furthermore, the ubiquitin-mediated protein degradation of EED was shown to restrict proliferative potential of cancer cells." (PMID 33882457, 2021). "Furthermore, NORED exclusive-associated genes were uniquely enriched in genes characterized by H3K27me3 with polycomb proteins (SUZ12 or EED) bound to promoters that experience de novo DNA methylation in cancers (18 genes, q=6.94×10−9)." (PMID 29387450, 2017). "Also, our work verified the possibility to the development of anti-cancer agents by disrupting the association of core PRC2 components EZH2 and EED." (PMID 25944687, 2015). "Therefore, allosterically targeting PRC2 activity by inhibiting EED action may offer a new and effective approach for renoprotection during cisplatin‐based cancer therapy." (PMID 35734954, 2022). "Interestingly, existing evidence also revealed that the dysfunction of the PRC2 complex comprising of subunits such as EZH2, SUZ12, and EED could expedite abnormal hypermethylation of H3K27 which induces carcinogenesis in a wide array of cancers." (PMID 33882457, 2021). "Cancers with high expression of the ES signature often show high expression of the PRC2 core components EZH2 and EED." (PMID 40678543, 2025).
cancer (continued). "By conducting a structure–activity relationship study that focused on exploring various linkers, we identified MS147, which preferentially degraded PRC1 components, BMI1 and RING1B, over PRC2 components: EED, EZH2, and SUZ12, in multiple cancer cell lines." (PMID 36737841, 2023). "EZH2 combines with EED, SUZ12, and RBBP4 to generate a PRC2 subunit, which is overexpressed in multiple types of cancer." (PMID 36686830, 2022). "Notably, less resistancewas observed during 43c treatment of Pfeiffer and KARPAS422DLBCL cell lines, therefore confirming that the PRC2 allosteric inhibitors(EED binders) could help to overcome the resistance induced by theEZH2 catalytic inhibitors in cancer therapy." (PMID 34351144, 2021). "Consistent with dysregulation of PRC2 in several human cancers, a robust expression of EZH2, SUZ12, and EED proteins was seen on the western blots for all MCL cell lines analyzed." (PMID 32850364, 2020). "Among the targets in our chemical probe collection, several have agents currently in clinical trials for cancer (EZH2, EED, DOT1L, PRMT1, and PRMT5) and additional PMT inhibitors are in preclinical studies." (PMID 30604761, 2019). "Recently, compounds that disrupt the interaction between EZH2 and EED have been developed, leading to the destabilisation and degradation of PRC2 proteins, which could provide a new avenue for cancer therapy." (PMID 39236081, 2024). "These PROTACs link a selective EZH2 inhibitor to the CRBN ligand 4-hydroxythalidomide and can degrade the proteasome of the PRC2 subunit in multiple cancer cell types, including EZH2, EED, SUZ12, and Retinoblastoma-binding protein 48 that can completely block EZH2." (PMID 36770884, 2023). "In contrast, EED inhibitors still show efficacy in suppressing the proliferation of these cells, suggesting the potential advantage of EED inhibitors for treating SAM-competitive EZH2 inhibitor-resistant cancers." (PMID 37909018, 2023). "The first PCR2-targeting PROTAC was composed of a target protein-binding ligand (EED) and an E3 ubiquitin ligase ligand (VHL) and could degrades PCR2 in cancer cells and inhibit cell proliferation in PRC2-dependent cancer cells." (PMID 36770884, 2023). "The exclusive activation of EED suggests a potential role for this gene in the transition from nonaggressive to aggressive cancer." (PMID 37175580, 2023). "We also sequenced the polycomb complex repressor 2 (PRC2) components EZH2, SUZ12, and EED, as frequently co-altered with RAS pathway genes in other cancers in 104 samples from our cohort, and found that 50% and 13.8% of RAS+ and RAS− cases, respectively had concomitant PRC2 alteration (p < 0.0001)." (PMID 35354920, 2022). "In addition, we found that EED, a core component of PRC2, and JARID2, an accessary factor of PRC2, were essential for TGF-β-induced EMT through CDH1 repression in cancer cells." (PMID 33779563, 2021). "Both EZH2 and EED degradation by EZH2–EED interactionimpairment (5b) or by EZH2–EED–PROTAC offera significant additional opportunity to block the PRC2 oncogenic activity,above all in the treatment of cancer types resistant to the EZH2 orthostericinhibitors." (PMID 34351144, 2021). "In conclusion, we identified that wedelolactone could bind to EED and target PRC2, thereby modulate its targets and cancer-related genes." (PMID 25944687, 2015). "Similarly, genes that become hypomethylated by functional depletion of CBX4 or RNF2, or by joint knockdown of EED and RNF2, are enriched for those that commonly become hypermethylated in human cancers." (PMID 25071008, 2014). "One of these compounds, wedelolactone, binds to EED with a high affinity (KD = 2.82 μM), blocks the EZH2-EED interaction in vitro, induces the degradation of PRC2 core components and modulates the expression of detected PRC2 downstream targets and cancer-related genes." (PMID 25944687, 2015).
infection (3 papers, 2016 to 2023). The state of being infected such as from the introduction of a foreign agent such as serum, vaccine, antigenic substance or organism. "Other epigenetic modulators like DNA demethylases TET2 and TET3, histone variant genes, INO80 complex, PRC2 complex genes, EED and SUZ12 were also associated with DNA methylation changes upon infection." (PMID 27112593, 2016). "Among the hits, EED, a core subunit of PRC2, has been reported to repress lytic gene expression during KSHV de novo infection; IRF8 positively regulates STING-mediated innate immune responses to inhibit HSV-1 replication." (PMID 37010434, 2023).
hematologic malignancies (2 papers, 2020 to 2024). "Notably, actionable or druggable gene mutations in EZH2, SUZ12, or EED are mostly observed in hematologic malignancies." (PMID 39565059, 2024).
inflammation (1 paper, 2022). Aberrant reaction of the microcirculation characterized by movement of fluid and leukocytes from the blood into extravascular tissues. "Therefore, EED mediated PRC2 activation is involved in the regulation of cisplatin‐induced renal inflammation in AKI mice, and its mechanism may be related to the activation of STAT3 and NF‐κB signaling pathways." (PMID 35734954, 2022).